IMP3 (IMP U3 small nucleolar ribonucleoprotein 3)
Diseases named in the same sentence as IMP3 in open-access papers (continued):
Sharing a sentence is not in itself a finding about the gene and the disease.
tumor (continued). "IMP3 has been reported to function by regulating tumor cell proliferation, migration and metastasis." (PMID 25295085, 2014). "Of these, 113 (59.2%) showed positive IMP3 expression that was predominantly localized to the cytoplasm of the tumor cells, along with faint nuclear staining." (PMID 25295085, 2014). "IMP3 has been shown to promote tumor cell proliferation through the upregulation of IGF2, a potent mitogenic factor previously shown to exert effects in a number of diseases." (PMID 25295085, 2014). "Studies have shown that the oncofetal protein, IMP-3, appears to play a critical role in arranging cellular proliferation, tumor invasion and aggressive behavior." (PMID 24137402, 2013). "The present data also suggested that the IMP3 protein was a significant proliferation marker for tumor cells." (PMID 24137402, 2013). "We tried to obtain this important prognostic information using antibody to oncofetal protein IMP3, previously identified as a marker of aggressive behaviour in various tumours." (PMID 23190601, 2012). "In contrast, the oncogene IGF2BP1-3 (IMP3, ↑8.793 fold) was highly over expressed in tumor relative to NB." (PMID 22280838, 2012). "The expression level of Imp3 also appeared directly related to tumorigenic ability in vivo which is the critical determination for tumor-initiating cells." (PMID 23226335, 2012). "In most studies increased expression of IMP3 correlates with aggressive biological behaviour of the tumour." (PMID 23190601, 2012). "Our results implicate Imp3 as a molecule capable of conferring critical properties to transformed cells for tumorigenic ability in vivo, which is indispensable for tumor-initiating cells, often consistent with cancer stem cells." (PMID 23226335, 2012). "Igf2 mRNA has been implicated as a main target of Imp3, and activation of Igf2 mRNA translation driven by Imp3 was previously found resulting in modulation of cellular functions such as proliferation and tumorigenic activity as well as tumor cell invasion." (PMID 23226335, 2012). "We then examined the expression of Imp3 in these tumor cells by establishing sublines after mechanical dissection and mincing of tumor tissues." (PMID 23226335, 2012). "Although the Imp3 expression in AX-low-a cells, which were established from the smallest tumor, was virtually identical to that in the parental AX-low cells, other established cells from larger tumors showed significantly higher level of Imp3 expression." (PMID 23226335, 2012). "In this study two different patient/tumor cohorts were analysed, so it is unlikely, that a larger cohort with even longer follow up times would demonstrate a prognostic value of IMP3." (PMID 20591150, 2010). "Recent studies have shown a remarkable overexpression of IMP3 in different human malignant neoplasms and also revealed it as an important prognostic marker in some tumor entities." (PMID 20591150, 2010). "The difference of IMP3 immunoreactivity between normal and tumor tissues was highly significant (p < 0.001)." (PMID 20591150, 2010). "Immunohistochemical detection of IMP3 has proven useful in predicting tumor progression and metastasis, suggesting that its inclusion in diagnostic panels could refine prognosis and guide treatment decisions." (PMID 41438588, 2026). "Insulin-like growth factor 2 mRNA-binding protein 3 (IMP3) has been implicated in tumor biology, but its role in cellular metabolism is not well characterized." (PMID 41614778, 2025). "In EC, IMP3 expression has been utilized to differentiate between cases of EEC and NEEC, as well as to identify associated pathogenetic and prognostic factors such as tumor differentiation and staging." (PMID 39176196, 2024). "Both ENCs and CCs demonstrated IMP3 immunoreactivity, with a higher frequency of expression in the CC group, which was directly proportional to the increase in the histological grade and, therefore, correlated with tumor progression." (PMID 39368400, 2024).
tumor (continued). "However, due to the frequent occurrence of IMP3 expression, especially in aggressive tumours, the target structure appears to be interesting for system therapies." (PMID 37627115, 2023). "It is known that IMP3 expression is different in the main tumour or satellite cells." (PMID 37627115, 2023). "In the literature, IMP3 is examined in many different tumour entities." (PMID 37627115, 2023). "There is also evidence of a link between increased IMP3 expression and advanced tumour stage." (PMID 37627115, 2023). "Overall, IMP2 (both clones) showed a higher percentage of positivity than IMP3 in all tumor types." (PMID 36740684, 2023). "The insulin-like growth factor 2 mRNA-binding protein 3 (IGF2BP3, also named IMP3) could be a tumour marker with such a potential." (PMID 37627115, 2023). "Finally, to confirm the anti-neoplastic effect of IMP3 silencing, we tested the ability of IMP3 knockdown to inhibit tumour growth in vivo." (PMID 37024466, 2023). "All tumor types showed higher expression of IMP2 (for both antibodies) compared to IMP3." (PMID 36740684, 2023). "High IMP3 expression is correlated with poorer prognosis in many tumour entities." (PMID 37627115, 2023). "The tumour marker IMP3 seems to be suitable for outcome prediction in LSCC and ECSCC." (PMID 37627115, 2023). "Additionally, IMP3-positive skin tumors exhibited higher Ki-67 labelling indices, suggesting increased proliferation of these tumor cells." (PMID 35892887, 2022). "Moderate to strong staining in at least 10% of tumor cells was considered positive IMP3 expression." (PMID 36577979, 2022). "In present study, we verified IMP3 was upregulated in CRC using TCGA public database and the cohort from our center, which was positively associated with the AJCC stage, tumor invasion depth, and nodular metastasis; furthermore, patients with higher IMP3 expression had poorer prognoses." (PMID 34154626, 2021). "The results showed U0126 could partially reverse the effects of IMP3 on tumorigenesis, and knockdown of IMP3 concomitant with U0126 treatment could further reduce tumor volumes and weights in vivo." (PMID 34154626, 2021). "Moreover, IHC of transgenic mice tumor tissue also showed that IMP3 expression level is positively correlated with MEKK1 expression level." (PMID 34154626, 2021). "Moreover, the present study has demonstrated that IMP3 expression correlated with poor prognostic indicators and tumor progression in cases of SCC on top of IP." (PMID 33680717, 2021). "In NCI-H1975 tumor-bearing mice, Imp3 could be detected in plasma and tissues within 0.5 h after dosing." (PMID 33986687, 2021). "Vascular invasion is also statistically significantly associated with expression of IMP3 and indicates greater invasiveness and metastatic ability of tumor cells by increasing cellular mobility and transendothelial migration in subjects with higher expression of IMP3." (PMID 34035433, 2021). "In such sense, IMP3's spatial varying expression patterns might indeed highlight the more potent population of tumor cells capable of survival, metastasis, and recurrence." (PMID 33680717, 2021). "Although the reason for this discrepancy is unknown, the results of this study were more plausible because IMP3 staining was believed to be positive even in small samples, if the tumor expressed any IMP3." (PMID 34446759, 2021). "LIN28B suppresses expression of Let-7 miRNA, a miRNA which can otherwise inhibit tumor cell migration and invasion by targeting IMP3; thus, IMP3 may regulate both development and the oncogenic processes of cancer." (PMID 34154626, 2021). "Therefore, an independent prognostic relevance was found for tumor size, clinical stage, and IMP3 immunostaining." (PMID 32049813, 2020). "Combined with the in vitro studies demonstrating a crucial role of IMP3 in the tumor proliferation and invasion, our findings further confirm that the overexpression of this protein is not involved in tumor initiation but may be involved in tumor progression." (PMID 31277094, 2019).
tumor (continued). "Molecules targeting IMP3 could be considered for attenuating and disrupting NF-κB thus ensuring pronounced tumor specific inhibition with minimum side effects." (PMID 28465487, 2017). "IMP3 is considered as an oncofetal protein and is related to tumor metastasis." (PMID 26837693, 2016). "Furthermore, IMP-3 ribonucleoproteins were demonstrated to operate as cytoplasmic safe houses that kept HMGA2 mRNA from miRNA-directed decay during tumor progression." (PMID 26796627, 2016). "IMP-3 expression in ALM tumor tissues could provide complementary prognostic information, in addition to the major clinicopathological features, which in turn could help to determine the best choice of therapy." (PMID 26796627, 2016). "Interestingly, we have found that IMP3 expression was highest in poorly differentiated, grade 3 tumours." (PMID 25886367, 2015). "IMP3 promotes the proliferation of tumor cells by increasing the translation of IGF-II mRNA." (PMID 25789070, 2015). "In addition, IMP3 reexpression is correlated with tumor aggressiveness and unfavorable prognosis and it is also considered a marker of preinvasive lesions." (PMID 25695077, 2015). "Only tumor IMP3 expression was associated with inferior OS, although not statistically significant (IMP3 negative 14.2 versus IMP3 positive 4.9 months; HR 0.46, 95% CI 0.16–1.21; P = 0.12)." (PMID 25688268, 2015). "IMP3 may be a potential IHC biomarker that can be used to evaluate the tumor progression and prognosis of ESCC." (PMID 25295085, 2014). "Immunohistochemistry for IMP3 may be a potential biomarker to evaluate the tumor progression and prognosis of CRA." (PMID 24137402, 2013). "Furthermore, Imp3 expression in a lethal tumor derived from AXT-sh2 cells at 141 days after intraperitoneal cell injection was also increased compared with the parental cells." (PMID 23226335, 2012). "The efficiency of Imp3 knockdown by shRNA might be reduced during tumor development with a long latency." (PMID 23226335, 2012). "Aberrant Imp3 expression in tumor cells may thus promote anchorage-independent growth and loss of contact inhibition." (PMID 23226335, 2012). "Also, knockdown of IMP3 inhibited allograft tumor progression in vivo." (PMID 38271139, 2024). "A new approach could be to adjust tumour follow-up care dependent on IMP3 expression." (PMID 37627115, 2023). "However, while an important role for IMP3 in the control of PDAC tumor progression by enhancing the pro-metastatic behavior of tumor cells is known, little is known about the role of IMP1 in PDAC progression, despite abundant data suggesting its real impact on the prognosis of PDAC patients." (PMID 37894350, 2023). "Moreover, to investigate whether the decreased HCT-116 derived tumor volume observed in IMP3 AS treated mice was due to an increase in cell death, we performed a terminal deoxynucleotidyl transferase dUTP nick end labeling (TUNEL)." (PMID 37024466, 2023). "However, IMP3 is reported to predominantly express in tumour tissues and in foetal tissues." (PMID 35315195, 2022). "In addition to the depth of invasion, it is speculated that tumor differentiation may be a factor affecting the rate of IMP3-positive cells." (PMID 34006250, 2021). "In contrast to the oncogenic role of IMP3, deletion of IMP1 in stromal cells in the same treatment model leads to increased tumor burden, suggesting an alternative tumor-suppressive function in certain tissue contexts." (PMID 40141058, 2025). "We successfully constructed organoids derived from the patient’s tumor samples, which expressed tumor-specific markers MUC-1 and IMP-3, as well as the proliferation marker KI-67." (PMID 40855305, 2025). "The other five top-rated CTAs CT45, IMP3, KIF20A, PRAME, and SP17 were similarly promising, and reached 8.07 points, due to a lower tier in “Expression on tumor Stem Cells”." (PMID 36768616, 2023).
tumor (continued). "To identify circRNPs with a specific protein component, we focused on IMP3 (IGF2BP3, insulin-like growth factor 2 binding protein 3), a known tumor marker and RNA-binding protein." (PMID 27510448, 2016). "The positive rate of IMP3 protein expression was 74.7% (139/186) in the NSCLC tissues and was significantly higher than the rate of 19.9% (37/186) in the adjacent non-tumor tissues." (PMID 25789070, 2015). "Given that a small fraction of AX cells (2.6±0.27%) was found to express Imp3 at a relatively high level in culture, we examined whether these few cells might preferentially expand and generate tumors in vivo or whether Imp3 expression becomes up-regulated during tumor formation." (PMID 23226335, 2012). "IMP3 is involved in RNA-binding and post-transcriptional regulation of oncogenes, and its role in epithelial-mesenchymal transition (EMT) further supports its relevance in tumor progression." (PMID 41438588, 2026). "Notably, IMP3−/− mice exhibit reduced MEKK1 expression and tumor burden following azoxymethane and dextran sodium sulfate treatment." (PMID 40141058, 2025). "For example, IMP3 suppressed the NKG2D ligand UL16-binding protein 2 (ULBP2) and indirectly downregulated MHC class I polypeptide-related sequence B (MICB), which facilitated tumour immune evasion." (PMID 39718205, 2025). "Besides, some genes which have close relationship with tumor metastasis such as choroideremia-like (CHML) and Insulin-like growth factor II mRNA-binding protein 3 (IMP3) are more abundant in satellite nodules." (PMID 38972883, 2024). "IMP3 is not expressed or weakly expressed in normal adult tissues, but it is highly expressed in various cancers and is closely related to tumor proliferation, invasion, and metastasis." (PMID 39328205, 2024). "The highest positivity of IMP3 according to the percentage of positive cells was found in MC (82% positive cases, 62% cases with expression in > 50% of tumor cells) and MBT (81% positive cases, 58% cases with expression in > 50% of tumor cells)." (PMID 36740684, 2023). "This correlation shows that IMP3 is unfortunately not specific to cSCC and can also be found in other tumour entities." (PMID 37627115, 2023). "Spearman's rho revealed that both IMP3 and Ki-67 were significantly related to the lymph node and tumor stages but not to the tumor grade." (PMID 33680717, 2021). "Our current work revealed that IMP3 expression was significantly related to lymph node and tumor stages, but not to tumor grade." (PMID 33680717, 2021). "Spearman's rho analysis revealed that both IMP3 and Ki-67 expressions were significantly related to lymph node and tumor stages, but not significantly related to tumor grade." (PMID 33680717, 2021). "IMP3 expression was characterized by heterogeneity among SCC cases, such that negative areas alternate with positive areas of low intensity cytoplasmic staining of tumor cells among well-differentiated SCC." (PMID 33680717, 2021). "The expression of IMP3 was highly related to advanced tumor stage (P < 0.001), advanced tumor grade (P = .004), and tumor recurrence (P < .001) in non-muscle-invasive urothelial carcinomas of the bladder." (PMID 31277094, 2019). "In the current study, we detected the expression of IMP3 in non-muscle-invasive urothelial carcinoma of the bladder, explored its correlation with tumor clinical characteristics, and evaluated its role in diagnosis and prognosis." (PMID 31277094, 2019). "As we expected, our findings indicated that tissue expression of IMP3 was highly related to advanced tumor grade and stage and to tumor recurrence in non-muscle-invasive urothelial carcinoma." (PMID 31277094, 2019). "IMP-3 expression did not correlate with age, sex, ulceration, metastatic nodes or tumor site in ALMs." (PMID 26796627, 2016).
tumor (continued). "Additionally, natural killer (NK) cells are known for their ability to recognize and eliminate tumour cells via natural killer group 2 member D (NKG2D) ligands, and are also influenced by RBPs such as insulin-like growth factor 2 mRNA-binding protein 3 (IMP3)." (PMID 39718205, 2025). "The immunoexpression of IMP3 was observed in 21 of 92 (22.82 %) cases, CDK4 in 13 of 94 (13.82 %) cases, MDM2 in 17 of 99 (17.17 %) cases, and β-catenin in 8 of 90 (8.8 %) cases, with no significance for percentage of positive cells between the analyzed tumor's group." (PMID 39368400, 2024). "Our results suggest that positive IMP3 expression was significantly related to poor survival, and these patients can consider direct radical cystectomy, while patients without IMP3 expression could be considered for transurethral resection of the tumor with postoperative intravesical chemotherapy." (PMID 31277094, 2019). "Those patients with tumor thickness ≤ 4.0 mm concomitant with positive IMP-3 expression had poorer OS, MSS, RFS and DMFS than ALM patients with thickness ≤ 4 mm and negative IMP-3 expression (P = 0.012, 0.048, 0.026 and 0.045, respectively; log rank test)." (PMID 26796627, 2016). "In the case of IMP3/IGF2BP3, staining was only detected in the smooth muscle cells across tumor and adjacent normal regions, but not in tumor, normal cells, or stroma (data not shown)." (PMID 22280838, 2012). "Neither tumor expressed IMP1 and only one of the tumors expressed IMP3." (PMID 29163784, 2017).